TAS2R42 (taste 2 receptor member 42)
Description:
Receptor that may play a role in the perception of bitterness and is gustducin-linked. May play a role in sensing the chemical composition of the gastrointestinal content. The activity of this receptor may stimulate alpha gustducin, mediate PLC-beta-2 activation and lead to the gating of TRPM5 (By similarity).
Synonyms: T2R42; T2R55; TAS2R55; T2R24; hT2R55
Tractability: Antibody: its Gene Ontology location is reachable by antibodies, with high confidence; UniProt predicts a signal peptide or a membrane-spanning region. PROTAC: a small molecule that binds it is known.
Target class: Membrane receptor; Taste receptor (taste family GPCR); Taste family G protein-coupled receptor
Gene: Protein-coding gene on chromosome 12 (11,185,993 to 11,186,937, reverse strand). Ensembl gene ENSG00000186136.
Subcellular location: Membrane
Pathways (Reactome):
Signal Transduction: Class C/3 (Metabotropic glutamate/pheromone receptors); G alpha (i) signalling events
Gene Ontology:
Molecular function: bitter taste receptor activity; G protein-coupled receptor activity
Biological process: detection of chemical stimulus involved in sensory perception of bitter taste; G protein-coupled receptor signaling pathway; sensory perception of taste
Cellular component: membrane; plasma membrane
Genetic constraint (gnomAD): Loss-of-function variants: 1 observed, 0.21 expected, observed/expected ratio (o/e) 4.68. That is too few expected variants to judge how well the gene tolerates losing a copy. Missense variants: 354 observed, 373.6 expected, observed/expected ratio (o/e) 0.95, 90% interval 0.87 to 1.03. Synonymous variants: 138 observed, 140.34 expected, observed/expected ratio (o/e) 0.98, 90% interval 0.86 to 1.13.
Homologues: Orthologues: chimpanzee TAS2R42 (97% identical), macaque TAS2R42 (88% identical), dog TAS2R42 (61% identical), rat Tas2r145 (48% identical), mouse Tas2r131 (46% identical). Paralogues in human: TAS2R7 (40% identical), TAS2R10 (35% identical), TAS2R3 (35% identical), TAS2R14 (35% identical), TAS2R9 (34% identical), TAS2R31 (33% identical), TAS2R46 (33% identical), TAS2R50 (33% identical), TAS2R43 (33% identical), TAS2R8 (33% identical), TAS2R30 (33% identical), TAS2R20 (32% identical), and 11 more.
Diseases named in the same sentence as TAS2R42 in open-access papers:
TAS2R42 is named in the same sentence as 2 diseases in open-access papers, as found by Europe PMC text mining. Sharing a sentence is not in itself a finding about the gene and the disease. The quoted sentences say what the papers report.
oropharyngeal cancers (1 paper, 2022). Carcinoma, predominantly squamous cell, arising from the epithelial cells of the oropharynx. "Understanding T2R42 function will be difficult with no known agonists, but TAS2R42 expression in tumor compared with normal tissue was altered in ∼ 89% of oral and oropharyngeal cancers in our TCGA analysis." (PMID 34717036, 2022).
TAS2R42 also shares sentences with these, for which no sentence is quoted: tumor (1 paper).